HDAC1 (histone deacetylase 1)
Diseases named in the same sentence as HDAC1 in open-access papers (continued):
Sharing a sentence is not in itself a finding about the gene and the disease.
cancer (continued). "Besides our former findings, the epigenetic inhibition of HDAC1 on miR-200b has also been validated in cancer stem-like cells." (PMID 35864549, 2022). "Indeed, HDAC1 inhibition has received attention for therapeutic purposes in solid tumors and hematologic malignancies, even though HDAC1 inhibitors have shown limited responses as single agents in patients with cancer." (PMID 35104240, 2022). "All of these pathways have been implicated in metastasis and/or poor cancer outcome; consistent with the differential expression of HDAC1/7-SE signature between metastatic BPLER vs. non-metastatic HMLER cells." (PMID 36038558, 2022). "We also used cisplatin as a control for the NANOG/HDAC1 axis–independent cancer drug." (PMID 35104240, 2022). "Additionally, pyrazole 5j showed the best activity against all tested cancer cells among the synthesized derivatives and the most selective binding to HDAC1 based on molecular docking experiments." (PMID 35630809, 2022). "The aim of the present study was to extract BSO from black seeds sourced from the local market of Al-Qassim, Saudi Arabia, to determine its content of TQ and to investigate its inhibitory effects on the expression of UHRF1, DNMT1 and HDAC1 and the related events in several cancer cells." (PMID 35566130, 2022). "Thus, understanding the role of the UHRF1/DNMT1/HDAC1/G9a complex in reading the epigenetic marks (DNA methylation and histone marks) in cancer will allow the development of a new generation of multitarget epidrugs." (PMID 33922029, 2021). "HDAC1 plays a role in cancer initiation and progression in many cancers by removing acetyl groups." (PMID 34262594, 2021). "In addition, HDAC1 is found increased in various cancers, nervous system and heart diseases, and so on." (PMID 34465322, 2021). "Similarly, SOX4 binds to the promoter of HDAC1 in all types of tested cells, indicating the mechanism that SOX4 transcriptionally activates HDAC1 is conserved in multiple types of cancer." (PMID 33482915, 2021). "In addition, several recent studies have shown that HDAC1 inhibition is beneficial to the therapy of cancer, thus highlighting the cancer promoting function of HDAC1." (PMID 34880761, 2021). "High expression levels of HDAC1 have been reported in diverse cancer types." (PMID 34635181, 2021). "In addition to the role that MDM2 plays in cancer regulation, it has also been shown to ubiquitinate Lys47 of HDAC1 in vascular calcification." (PMID 34577077, 2021). "Thus inhibitors of p300 and inducers of HDAC1 have therapeutic implications in the treatment of cancers that have high expression of Api5." (PMID 34385547, 2021). "Several HDAC1 inhibitors have been developed for anti-cancer applications." (PMID 33482915, 2021). "The discovery of IDO1 and HDAC1 dual inhibitors may provide a novel strategy for cancer treatment by taking advantages of both immunotherapeutic and epigenetic drugs." (PMID 33007982, 2020). "A growing line of evidence has shown that HDAC1 could affect various oncogenic processes, such as cell proliferation and invasion, in multiple malignant tumors." (PMID 32807131, 2020). "An anomalous histone acetylation, and consequently an alteration in the expression of HDACs, is related to cancer Likewise, an overexpression of HDAC1 and HDAC2 has been found in LC, and HDAC8 knockdown leads to the inhibition of cell proliferation in lung and other types of cancer." (PMID 30759767, 2019). "The investigation showed that Slug SUMOylation might increase corepressor, HDAC1, recruitment, inhibit downstream target genes expressions, and have end result in promoting cancer malignancy." (PMID 30612578, 2019). "In addition to compounds used in psychiatry, LINCS analysis revealed an anti-cancer drug, vorinostat, a histone deacetylase inhibitor (HDAC1–3 and 6) as an upregulator of Cepbd." (PMID 29482641, 2018). "HDAC1 over-expression is related to the development of some cancers." (PMID 30533999, 2018).
cancer (continued). "Moreover, two HDAC1/2-derived HLA ligands activate T-cells, prompting further elimination of HLA-matched cancer cells." (PMID 30064416, 2018). "In addition, UHRF1 binds to methylated promoters of many tumor suppressor genes by forming complexes with DNMTs and HDAC1, resulting ultimately in the formation of cancer." (PMID 28241740, 2017). "Indeed, several reports indicated that HDAC1 is up-regulated in many cancer cell lines and tissues, including GC, at both the transcriptional and translational levels." (PMID 28129645, 2017). "Taken together, our results indicate that HDAC1 and HDAC2 positively regulate activation of the FA pathway and that cellular sensitivity to ICL-inducing agents, which are widely used in cancer chemotherapy, may be increased via HDAC1/2 inhibition." (PMID 29100324, 2017). "Therefore, the inhibition of HDAC1 was responsible for the pan-HDAC inhibitor-induced enhancement of statin anti-cancer effects." (PMID 28481295, 2017). "Inhibition of HDAC1 could enhance statin-induced inhibition of cell proliferation, apoptosis, migration, and invasion in two cancer cell lines." (PMID 28481295, 2017). "Aberrant expression of HDAC1 has been found in various types of cancers, which indicates that it might be a target for cancer therapy." (PMID 28900297, 2017). "We next examined whether GGTase-Iβ mediated the enhancement by pan-HDAC inhibitor or HDAC1 inhibitor of anti-cancer effects of statins in cells." (PMID 28481295, 2017). "Given that a combination of statin and HDAC1 inhibitor produced a synergistic anti-cancer effect, this combination could be a potential new regimen in cancer chemotherapy." (PMID 28481295, 2017). "Moreover, HDAC1 inhibitor for the treatment of different types of cancer, including GBM, not only as a single agent, but also in combination with other anticancer agents, has been widely tested in clinical trials." (PMID 28624794, 2017). "In addition, the HDAC1 expression level was higher in patients with low-differentiated cancer than that expressed in those with moderate/high-differentiated gastrointestinal cancer (OR = 1.75, 95% CI = 1.03–2.95, P = 0.04)." (PMID 28424407, 2017). "Interestingly, we also observed increased HDAC1 protein levels in cancer cells, which is opposite to the increased K9 acetylation." (PMID 29057918, 2017). "Inhibiting HDAC1 could enhance the anti-cancer effects of statins through downregulation of GGTase-Iβ expression both in vitro and in vivo, without severe damage to non-tumor cells." (PMID 28481295, 2017). "The expression of HDAC1 in different cancers has been reported recently." (PMID 28624794, 2017). "It has previously been shown that HDAC1, HDAC3, and HDAC4 might be associated with resistance to chemotherapy and poor prognosis in cancer patients." (PMID 26683361, 2016). "The results suggest that blocking Per2 or HDAC1 may be a valuable remedy to prevent cancer metastasis." (PMID 26898709, 2016). "HDAC1 affects a variety of processes including proliferation, development, metabolism, and cancer." (PMID 27852975, 2016). "Furthermore, these findings disclose a new role for HDAC1 in governing transcription of the oncogenic Cancerous Inhibitor of Protein Phosphatase 2A (CIP2A) that is known to be overexpressed in numerous cancers including CRCs." (PMID 27029072, 2016). "We next investigated the effect of Hdac1 and Hdac2 ablation in the Eμ-myc cancer background, and in particular whether they have tumor suppressive or tumor promoting functions during Eμ-myc tumorigenesis." (PMID 27886239, 2016). "HDAC expression is generally elevated in cancer for example HDAC1, 2, 3 and 6 are reported to be upregulated in various cancers but some HDACs, such as HDAC1, 2 and SIRT1, may also be lost or decreased." (PMID 26426052, 2015). "Given their deregulation in cancer HDAC1 and HDAC2 are important therapeutic targets." (PMID 25970771, 2015).
cancer (continued). "Interestingly, UHRF1 also plays a role in recruiting HDAC1, which we also found consistently overexpressed in cancer, and which correlated specifically with DNA hypomethylation." (PMID 26169266, 2015). "HDAC1 is an especially attractive target because it is known to control levels of histone acetylation, which determines cell cycle progression, rates of proliferation, apoptosis and differentiation of cancer cells." (PMID 24830454, 2014). "Our experimental evidence with maspinD346E raised the importance of maspin molecular partnership that can be dictated by maspin sequence and may be used as the basis for better design of maspin-mimetic HDAC1-targeted anti-cancer drugs." (PMID 24278104, 2013). "Vorinostat and Flavopiridol are anti-cancer agents involving the HDAC1, HDAC2 and CDK1 genes." (PMID 24564241, 2013). "Under pathological conditions, such as cancer, the overall expression level of HDAC1 is increased." (PMID 24278104, 2013). "While the shift in the subcellular localization of maspin from the nucleus to the cytoplasm during cancer progression may be an early marker for tumor progression, HDAC1 is also shown to be differentially regulated during tumor progression." (PMID 24278104, 2013). "Silence of HDAC1 by small interference RNA (siRNA) or specific inhibitor MS-275 in cancer cells can either arrest at the G1 phase of the cell cycle or at the G2/M transition, resulting in the loss of mitotic cells, cell growth inhibition, and increase in the percentage of apoptotic cells." (PMID 22496786, 2012). "We show that gain-of-function cancer mutations in the KBTBD4 E3 ligase promote neodegradation of substrates via a shape-complementarity-based mechanism, which converges with the mechanism of action of the UM171 molecular glue degrader and can be blocked by HDAC1/2 inhibitors." (PMID 39939763, 2025). "We speculate that there are fewer mutations in the genetic content of chromosome HDAC1 in LUAD tissues, but the highly expressed promoter in cancer tissues participates in assisting the expression of HDAC1, thereby increasing the efficiency of transcription or translation." (PMID 36644230, 2023). "Therefore, the identification of novel small molecules targeting the E2F1/Rb/HDAC1 complex may provide a more effective therapeutic strategy for cancer." (PMID 38062013, 2023). "Indeed, several studies reported that HDAC1 represses Wnt signaling, an evolutionarily conserved pathway, in the regulation of cell proliferation, cell polarity, and cell fate determination during embryonic and cancer progression." (PMID 36230720, 2022). "Moreover, butyrate decreased the reverse expression of HDAC1 in human esophageal 9706 cancer cells." (PMID 35458763, 2022). "However, intracellular S1P may also promote cancer progression via intracellular targets, such as HDAC1/2 and NF-κB, and can promote cancer cell resistance to therapy by counteracting the pro-apoptotic effects of ceramide." (PMID 35159039, 2022). "Interestingly, TQ showed a stable interaction with the zinc ion that was found in the active site of the HDAC1, which played a crucial role in maintaining the stability of the protein catalytic site, indicating that TQ is a specific regulator of HDAC1 in cancer." (PMID 35566130, 2022). "Moreover, the results of RT-qPCR and Western blot indicated that these peptides may serve their function by inhibiting HDAC1 activity and modulating cancer-related gene expression." (PMID 35053925, 2022).
cancer (continued). "However, in breast cancer cell lines, where PIAS4 is overexpressed, it has been observed that PIAS4 preferentially binds SUMO2 to HDAC1, protecting it from ubiquitination and degradation, and promoting its expression and activity that is involved in cancer progression." (PMID 35887358, 2022). "Given that HDAC1 overexpression and EGFR activity are strongly related with tumor progression and cancer cell survival, HDAC1 tyrosine phosphorylation may present a possible target to manipulate HDAC1 protein levels in future potential cancer treatment strategies." (PMID 33976119, 2021). "Through above analysis, we noticed that HDAC1, identified in ‘Module 4’ from PPI network,which involves in Wnt signaling, also plays critical roles in three stemness-associated pathways identified in pathway analysis: ‘Notch’, ‘cell cycle’, and ‘transcriptional misregulation in cancer’." (PMID 33482915, 2021). "Our bioinformatics study showed that HDAC1 may mediate the regulatory effect of SOX4 on several important signaling pathways associated with stem cell maintenance, including Wnt (module 4), PPAR, Notch and transcriptional misregulation in cancer." (PMID 33482915, 2021). "HDAC1 inhibitors such as MS-275 have already been tested in many clinical trials for anti-cancer treatment 23, 46, thus they could be clinically effective tools to enhance β-cell function through triggering serotonin production, as supported by amplified insulin response in MS-275-injected mice." (PMID 32641996, 2020). "However, it was unexpected that hypermethylated genes would continue to be repressed after UHRF1 depletion, as it is well documented that UHRF1 acts as a hub to recruit multiple proteins, including DNMT1, HDAC1, G9a, and EZH2, to repress cancer-associated genes in cancer cells." (PMID 31064417, 2019). "Considering that a strong expression of HDAC1 was correlated with poor prognosis in cancer patients, and that HDAC1 is also overexpressed in cancer stem cells and modulates their function, the inhibition of HDAC1 could be an important strategy in cancer treatment." (PMID 28481295, 2017). "The information implies that the inhibition of HDAC1 may suppress cancer metastasis." (PMID 26898709, 2016). "Among them, St.38 exhibited strong antiproliferative activity across multiple cancer cell lines and potently inhibited CDK9, HDAC1, and HDAC3." (PMID 41440016, 2025). "Among them, HDAC1 and HDAC2 are particularly significant in neural progenitors and are frequently overexpressed in neural-derived cancers." (PMID 40640468, 2025). "Zinc‐dependent HDACs can be subdivided into four classes (class I–IV) based on sequence similarity to yeast deacetylases, among which class I HDACs (HDAC1, HDAC2, HDAC3, and HDAC8) are well studied and proved to be closely related to the development of cancer." (PMID 41267925, 2025). "Our bioinformatics analyses utilizing online open-source datasets demonstrated that the HDAC1 overexpression in TNBC correlates with poor prognosis, highlighting its significance in cancer progression." (PMID 40475010, 2025). "Histone deacetylase 1 (HDAC1) is a member of the class I HDAC family and has emerged as a promising target in various diseases, including cancer and neurodegeneration." (PMID 39752394, 2025). "Entinostat selectively inhibits class I and II HDACs, especially HDAC1 and HDAC2, with potential applications across various cancers." (PMID 40284412, 2025). "Further investigations utilizing the UALCAN database revealed that HDAC1 expression was particularly elevated in TNBC, suggesting a potential link between HDAC1 and aggressive cancer phenotypes." (PMID 40475010, 2025).
cancer (continued). "Among them, St.39 underscored potent inhibition of both PI3K isoforms (IC50 = 2.5–80.5 nM) and HDAC1–3 (IC50 = 1.9–75.5 nM), exhibiting strong antiproliferative effects across multiple cancer cell lines." (PMID 41440016, 2025). "Analysis of CRISPR data from DepMap reveals weak overall dependencies of HDAC1 and HDAC2 across cancer cell lines, likely because one compensates in the absence of the other." (PMID 40479062, 2025). "Among histone deacetylases, HDAC1 and HDAC2 (Class I) showed reduced expression in carcinomas compared to normal tissues." (PMID 40590021, 2025). "Conversely, HDAC1, HDAC10, KAT2A, SIRT6, and SIRT7 were upregulated in 13, 16, 17, 14, and 12 cancer types." (PMID 39906742, 2024). "FUS has been shown to directly interact with HDAC1, a protein which has been shown to upregulate PP2A-C expression when hyperactive in cancer cell lines." (PMID 38363426, 2024). "The ability of compounds 76a–o to inhibit recombinant human HDAC1, HDAC3, and HDAC6 isoforms and ‘in vitro’ activity against cancer cell lines RMPI 8226 and HCT 116 was tested." (PMID 38202821, 2024). "The inhibitory activity of the series 92a–d towards HDAC1, HDAC3, and HDAC6 isoforms and cancer cell proliferation were evaluated." (PMID 38202821, 2024). "Related studies have shown that HDAC1 gene expression is highly expressed in LUAD tissues, and the related pathway affected by HDAC1 is closely related to the formation of cancer tissues." (PMID 36644230, 2023). "In these cancer cells, (R)-9-HSA upregulates p21WAF1, inhibits cell growth by targeting histone deacetylase 1, and interferes with EGF signaling." (PMID 37241793, 2023). "GTPases, such as RAC1, can activate EMT in multiple cancers, thus leading to a more invasive and drug resistant phenotype and we show that RAC1 expression is increased upon HDAC1 overexpression in PDAC cells." (PMID 37996815, 2023). "It will be interesting to explore the extent of the antagonistic relationship between HDAC1 and p300 in controlling EMT in normal development and cancer pathogenesis." (PMID 37414747, 2023). "HDAC1 regulates the acetylation of histone and non-histone proteins to modulate gene expression and its overexpression has been associated with progression, metastasis, and patient prognosis in many cancer types including gastric, breast, colon, and prostate cancers." (PMID 37996815, 2023). "HDAC1 and HDAC2 depletion rendered cancer cells hypersensitive to IR and resulted in diminished DSB repair capacity, particularly by nonhomologous end-joining." (PMID 37991020, 2023). "Endogenous HDAC1 suppresses, whereas endogenous p300 promotes EMT in epithelial and carcinoma organoids." (PMID 37414747, 2023). "In this study, we found that NANOG was associated with an immune-refractory feature of the TME and poor clinical outcomes in patients with cancer and that NANOG expression influenced the sensitivity of tumor cells to HDAC1 inhibitors." (PMID 35104240, 2022). "Both HDAC1 and HDAC2 are involved in regulation of cell cycle, cellular senescence and cancer progression." (PMID 35563824, 2022). "Knockdown of NANOG or HDAC1 with a siRNA robustly dampened expression of the effectors of NANOG signaling, such as CXCL10 and MCL1, across all tested cancer cells." (PMID 35104240, 2022). "Compound 12a which possessed good inhibitory potency against ALKwt and HDAC1, exhibited stronger antiproliferative activity than Ceritinib on ALK positive cancer cell lines though inducing cell apoptosis and cell cycle arrest in vitro and in vivo." (PMID 36100230, 2022). "PARP1 maintains cellular functions, including DNA repair/maintenance of genomic integrity, DNA methylation, chromatin regulation, and histone modification and helps in the recruitment of HDAC1 and HDAC2 as chromatin modifications in cancer." (PMID 35059624, 2022).